PYY (peptide YY)
Diseases named in the same sentence as PYY in open-access papers (continued):
Sharing a sentence is not in itself a finding about the gene and the disease.
diabetes (55 papers, 2008 to 2025). "An inverse correlation has been demonstrated between PYY levels and the development of cardiovascular risk factors (diabetes, hypertension, and hypercholesterolemia) and the risk of cardiovascular events." (PMID 39124846, 2024). "An inverse correlation has been demonstrated between PYY levels and cardiovascular risk factors (diabetes, hypertension, and hypercholesterolemia) and the risk of cardiovascular events." (PMID 39124846, 2024). "PYY which is present in both the intestine and various sub-types of islet cells, has been implicated in ameliorating diabetes in rodents and man after RYGB surgery." (PMID 36137097, 2022). "Moreover, PYY levels were significantly associated with age and cardiovascular risk factors, including hypertension, diabetes, and kidney function, in addition to biomarkers of heart failure and inflammation in patients with acute myocardial infarction." (PMID 36313742, 2022). "In addition, a correlation with the PYY level has been demonstrated for cardiovascular risk factors (diabetes, hypertension, and hypercholesterolemia) and cardiovascular events." (PMID 35330038, 2022). "Early presentation of food to the ileum may haveinduced the production of incretins such as GLP-1 and PYY which, together withglycemic control, contributed to weight loss, diabetes remission and theconsequent good surgical prognosis of these patients." (PMID 26734798, 2015). "PYY has gained prominence as a possible mediator of diabetes remission after bariatric surgery, with emerging evidence implicating it in hormonal regulation, appetite modulation, and broad metabolic adaptations." (PMID 41228539, 2025). "Phenylalanine stimulates the release of glucagon-like peptide-1 (GLP-1) and peptide tyrosine–tyrosine (PYY), decreases plasma ghrelin, stimulates the release of insulin, improves glucose tolerance in rats, and affects the development of diabetes." (PMID 35431942, 2022). "Consistent with PYY being associated to cardiovascular risk factors and diabetes, we found significantly more patients in the highest PYY tertile to receive blood pressure and diabetes medication in addition to lipid-lowering drugs and antiplatelet therapy." (PMID 33291235, 2020). "The highest postprandial concentrations of PYY were observed in men with diabetes, being higher than in obese men and twice higher than in healthy men." (PMID 30642053, 2019). "Taken together our data demonstrate that PYY is a critical humoral factor which mediates enhanced islet secretory function, thus contributing to diabetes remission in humans upon bariatric surgery." (PMID 30639417, 2019). "It seems that the synthesisof PYY decreased prior to the onset of diabetes, although the number of PYY cells wasunaffected." (PMID 23292145, 2013). "Abnormalities in PYY have beenreported in patients with diabetes type 1, and in animal models of human diabetes." (PMID 23292145, 2013). "For example, plasma PYY levels after consuming a mixed meal are significantly reduced in subjects with T2D compared to non-diabetic controls, indicating a diminished L-cell response or disrupted gut hormone signaling in diabetes." (PMID 41228539, 2025). "GLP-1, GLP-2, and PYY lower glucose concentrations, intestinal permeability, cytokine and amylase release, thereby improving metabolic disorders and inflammation during diabetes." (PMID 37692402, 2023). "Recent studies have reported that probiotic intake could increase the secretion of hormones, such as GLP-1 and PYY, by regulating the gut microbiota and their metabolites to prevent diabetes." (PMID 34955840, 2021). "PYY was also studied as a key factor in the remission of diabetes after bariatric surgery in rats." (PMID 32121443, 2020). "PYY levels were significantly associated with age and cardiovascular risk factors, including hypertension and diabetes, but not smoking or hypercholesterolemia." (PMID 33291235, 2020). "PYY is found in the pancreas and its relationship with diabetes was studied." (PMID 32121443, 2020).
diabetes (continued). "To date, the role of IL-22 in weight-loss surgery and diabetes remission in man has not been explored, and its potential impact on islet-derived PYY has not been determined." (PMID 30639417, 2019). "In clear contrast to healthy islets, PYY content has recently been shown to be reduced by 50% in islets from the Goto-Kakizaki (GK) rat model of T2D, suggesting a role of islet-derived PYY in health and diabetes." (PMID 30639417, 2019). "Enhancing endogenous PYY activity or using pharmacological agents that mimic PYY signaling may, therefore, represent a promising therapeutic strategy by stabilizing postprandial glucose levels—a primary objective in diabetes care, especially for individuals at elevated cardiovascular risk." (PMID 41228539, 2025). "Therefore, higher levels of adiposity and/or insulin resistance may be acting to negate exercise-induced changes in circulating total PYY in our study population with non-diabetic hyperglycaemia." (PMID 40425789, 2025). "Induction of diabetes caused a slight rise in PYY serum levels compared to the nondiabetic animals." (PMID 39337311, 2024). "The response in glucose, glucagon and PYY was higher among participants with T2D, compared to participants with pre-T2D, with either pre-load (e.g. p-value for the multiplicative interaction between diabetes status and the swallowed pre-load was 0.01 for glucose and <0.001 for insulin)." (PMID 37624823, 2023). "SCFAs were believed to be the crucial molecules that alleviated diabetes via greater postprandial glucagon-like peptide 1 (GLP-1) and fasting peptide YY (PYY)." (PMID 36557760, 2022). "SCFAs are a regulatory signal of metabolism that can directly activate G protein-coupled receptor 43 (GPR43), promote the secretion of glucagon-like peptide-1 (GLP-1) and peptide YY (PYY), improve fasting hyperglycemia, and delay the development of diabetes." (PMID 33817264, 2020). "Studies have shown that SCFAs play a significant role in the treatment of diabetes by influencing the secretion of GLP-1 and PYY, inflammation, etc.." (PMID 31396097, 2019). "Age, sex, BMI, reconstruction type, diabetes duration, preoperative blood glucose, HbA1c, insulin, C-peptide, HOMA-IR, ghrelin, leptin, GIP, PYY, and GLP-1 were analyzed." (PMID 29216250, 2017). "Diabetes medication status, biochemical and hormonal data including blood glucose, HbA1c, insulin, C-peptide, HOMA-IR, ghrelin, leptin, GLP-1, PYY, and GIP were evaluated for 12 months after surgery." (PMID 29216250, 2017). "As we induced diabetes into the rats, the serum concentration of PYY slightly increased, but there was no change in GLP-1 and GIP compared to the normal controls." (PMID 39337311, 2024). "Consistent with others, we found PYY serum levels to increase with age and to be elevated in patients with diabetes, which has similarly been reported by some although not all investigators." (PMID 33291235, 2020). "Post-test results indicated that plasma PYY concentration was lower in all groups except for obese diabetic training than control normal without diabetes (P = 0.001)." (PMID 31275881, 2019). "Chronic treatment of human isolated islets from diabetic and non-diabetic donors with exogenous PYY enhances glucose-mediated insulin secretion and improves suppression of glucagon, suggesting a direct effect of PYY on the correction of human diabetes." (PMID 30639417, 2019). "Increased secretion of the anorexigenic enterohormone PYY after IIP may also be involved in weight reduction and long-term improvement of diabetes." (PMID 26185767, 2015). "This potential central role of PYY in this physiological mechanism of action is not surprising in consideration that PYY improves glycemic control and suggests a possible PYY based therapy for the treatment of diabetes." (PMID 35405964, 2022).
diabetes (continued). "In the pancreas, while PYY and PP are expressed by α-cells and pancreatic PP cells, respectively, recent studies have demonstrated that NPY expression in mouse islet β-cells may play a role in altered β-cell function that precedes diabetes onset." (PMID 34890851, 2022). "However, the relationship between elevated circulating PYY and the metabolic benefits of bariatric surgery on islet secretory function and diabetes reversal has not been explored in humans." (PMID 30639417, 2019).
Insulin resistance (51 papers, 2012 to 2026). Increased resistance towards insulin, that is, diminished effectiveness of insulin in reducing blood glucose levels. "Similarly, studies on saccharin consumption in Wistar rats revealed weight gain without an increase in total caloric intake or associations with insulin resistance, fasting leptin, or peptide YY (PYY) levels." (PMID 40873447, 2025). "Additionally, compared to individuals with normal glucose regulation, an attenuated postprandial total PYY response to meal intake has been reported in individuals with impaired glycaemic control, insulin resistance or genetic susceptibility to type 2 diabetes." (PMID 40425789, 2025). "This review aims to clarify the biological characteristics and signaling mechanism of PYY, and explore its potential applications in improving insulin resistance." (PMID 41788781, 2026). "In another study however, first degree relatives of patients with T2DM had lower basal PYY than the control group, which was negatively correlated with insulin resistance." (PMID 41575482, 2026). "Both GLP-1 and PYY have been found to inhibit appetite, reduce body weight, and improve insulin resistance in obese mice." (PMID 36992691, 2023). "The elevation of FFAR2, FFAR3, GLP-1, and PYY by DOP treatment was another mechanism of insulin resistance improvement in prediabetic mice." (PMID 37372523, 2023). "GLP-1 and PYY contribute to satiety, reduction of plasma glucose and lipids, insulin resistance and inflammation, and increased lipid oxidation." (PMID 37469434, 2023). "SCFAs can also ameliorate insulin resistance by fostering the synthesis and release of PYY and GLP-1 in the intestinal epithelial gland cells." (PMID 37808975, 2023). "In addition, the upregulation of FFAR2, FFAR3, GLP-1, and PYY was reported to improve insulin resistance." (PMID 37372523, 2023). "However, other studies have found that fasting GLP-1 and PYY concentrations are significantly higher in patients with insulin resistance and T2D, compared to those with NGT." (PMID 37910328, 2023). "Interestingly, increases in the population of GLP-1 and PYY can significantly ameliorate the insulin resistance and glucose homeostasis of T2DM." (PMID 33817264, 2020). "Similarly, a previous study suggested that both insulin resistance and abnormal glucose metabolism impaired the PYY response to fat intake." (PMID 25222490, 2014). "However, among the results of a study designed to investigate various metabolites in insulin resistance, we discovered that PYY concentration was greater among obese subjects compared to normal-weight subjects." (PMID 24743402, 2014). "The presence of similar abnormalities in AD brains suggests that leptin and PYY levels could also serve as indices of brain insulin resistance." (PMID 25035815, 2013). "In adipose tissue, PYY may facilitate lipid mobilization and indirectly improve insulin sensitivity by mitigating inflammation and reducing adipocyte hypertrophy—both of which are characteristic features of insulin resistance." (PMID 41228539, 2025). "The underlying mechanism is open to speculation but may include persistence of the central leptin and insulin resistance associated with DIO and/or dominance of gut satiety hormone (PYY) signalling over the metabolic hormone feedback to hypothalamic appetite regulatory pathways." (PMID 26447990, 2015). "Symbiotic treatment improved the status of BMI, FBS, insulin resistance, HOMA-IR, GLP-1, and PYY in patients with metabolic syndrome." (PMID 38337675, 2024). "Insulin resistance analysis reveals that both OCA and Fer-1 significantly increase the serum level of PYY and the relative expression of PPARγ in the liver." (PMID 36588706, 2022). "Our data demonstrate that cold stress induced a wide range of physiological changes, such as increased insulin resistance and IgA levels and decreased cortisol, T3, T4, leptin, adiponectin, GLP-1, and PYY levels." (PMID 35383199, 2022).
Insulin resistance (continued). "Evidence of whether L-Phe reduces food intake; stimulates the release of CCK, PYY, or GLP-1; and is related to insulin resistance seems to vary across species of experiments and levels of L-Phe intake." (PMID 40588730, 2025). "Here, we have shown that RDX8940 is a potent, selective, and minimally systemic oral TGR5 agonist that induces GLP-1, GLP-2, and PYY secretion from mouse intestinal L cells and improves liver steatosis and insulin sensitivity in a model of NAFLD and mild insulin resistance." (PMID 30605011, 2019). "Gastric cancer surgery led to decreased ghrelin and leptin and increased PYY and GIP, which might have a role in improving insulin resistance and glucose homeostasis." (PMID 29216250, 2017). "Peptide YY (PYY) is a gut hormone primarily released from endocrine cells of the distal digestive tract which plays an important role in regulating food intake and energy balance, and is related to diabetes type 2 and insulin resistance." (PMID 28448466, 2017). "After gastric cancer surgery, ghrelin and leptin levels were decreased and PYY and GIP levels were increased, which may have a role in improving insulin resistance." (PMID 29216250, 2017). "Additionally, SCFAs produced by probiotics may decrease insulin resistance by increasing glucagon‐like peptide‐1 (GLP‐1) and peptide YY (PYY)." (PMID 40735396, 2025). "Furthermore, SCFAs might increase anorectic gut hormone secretion, PYY and GLP-1, which may enhance glucose disposal and decrease insulin resistance." (PMID 37929031, 2023). "Previously, in this cohort, we have reported metabolic inflexibility in response to a high-fat meal and a blunted peptide YY (PYY) increment in response to a high-carbohydrate meal, both of which may contribute to later insulin resistance, weight gain, and eventual T2D." (PMID 22474579, 2012). "This comparative study on clinical effects has some limitations that include lack of data collection on insulin resistance alleviation degree and lack of gastrointestinal GLP-1, GIP, and PYY hormones data collection." (PMID 26198306, 2015).
Anorexia (33 papers, 2006 to 2025). Lack of desire to eat (loss of appetite). "For instance, NYT has been shown to be effective in improving cisplatin-induced anorexia and altering the levels of peptide YY and ghrelin." (PMID 39398850, 2024). "In obese participants, diet-induced PYY secretion decreased, but the anorexia effect of PYY seemed to be intact." (PMID 38725663, 2024). "It has been suggested that a decrease in AG alongside increases in GLP-1, PP, and PYY in individuals with normal glucose tolerance levels mediate the effect of exercise-induced anorexia." (PMID 38674817, 2024). "PYY and ghrelin are key contributors to the development of anorexia–cachexia syndrome in paediatric patients with ALL." (PMID 39683512, 2024). "Increases in CCK, GLP-1, and PYY are thought to be closely related to anorexia and therefore affect muscle, and this relationship has also observed in sarcopenia patients with liver cirrhosis." (PMID 35565864, 2022). "DON-induced anorexia is partly due to the up-regulation of central anorexigenic factors and the massive release of the peripheral satiety hormones, such as peptide YY(PYY)." (PMID 36548782, 2022). "Our findings here demonstrate that DON rapidly induces four intestinal hormones CCK, GLP-1, GIP, and PYY in the plasma of mice; the way this increase occurs is consistent with the induction of anorexia." (PMID 34437383, 2021). "As an important satiety hormone, PYY can induce anorexia by upregulating anorexia signaling molecules." (PMID 34437383, 2021). "Glucagon-like peptide-1 (GLP-1), Oxyntomodulin (OXM), and Peptide YY (PYY) are anorexia-inducing hormones secreted from the neuroendocrine L cells of the gut in response to nutrients." (PMID 28379519, 2017). "In sum, our data suggest that SJDBT ameliorates cancer-associated anorexia/cachexia by regulating cytokines (IL-6 and MCP-1) and hormones (GLP-1 and PYY)." (PMID 24963216, 2014). "Moreover, our suggestion that GLP-1 and PYY contribute to transient anorexia as an adaptive response to SAM requires validation." (PMID 40944251, 2025). "Therefore, it has the ability to block Y2R in the central and peripheral areas, and can comprehensively explore the role of NPY2 receptor and PYY in DON-induced anorexia." (PMID 34437383, 2021). "Here, PYY administered by intraperitoneal injection caused mice to refuse to eat, indicating that this hormone might be the cause of the DON-induced anorexia." (PMID 34437383, 2021). "Consequently, it seems most beneficial for future interventions to target CCK, leptin, PYY and insulin when investigating methods to augment energy intake to reduce the anorexia of ageing from an endocrine perspective." (PMID 31432431, 2020). "Meanwhile, GLP-1, PYY, ghrelin, and leptin are known as readouts for anorexia/cachexia." (PMID 24963216, 2014). "Importantly, antagonist of the PYY receptor partially prevents the anorexigenic effect of DON, showing that PYY plays a role in the anorexia induced by DON." (PMID 23612752, 2013). "Research also indicates abnormal dynamic levels of PYY and ghrelin in anorexia and bulimia nervosa." (PMID 16420657, 2006). "Thus, the suppression of endogenous PYY in our study may represent a compensatory mechanism for protection against excessive anorexia." (PMID 41405347, 2025). "The researchers then explored the mechanism of Clpb-induced anorexia and found that Clpb increased PYY secretion in primary cultured cells of rat intestinal mucosa in a dose-dependent manner, demonstrating that Clpb activates the appetite signalling pathway mediated by PYY to suppress food intake." (PMID 37686760, 2023). "However, when the C-terminus of PYY3–36 is removed, PYY-induced anorexia also disappears, demonstrating that the integrity of the C-terminus may be essential for PYY to maintain its biological activity." (PMID 37686760, 2023).